STAT1 (signal transducer and activator of transcription 1)
Diseases named in the same sentence as STAT1 in open-access papers (continued):
Sharing a sentence is not in itself a finding about the gene and the disease.
cancer (continued). "Briefly, they showed that exosomes secreted by stromal fibroblasts activate the anti-viral machinery in cancer cells via STAT1, which, in turn, drives the expression of interferon-stimulated genes (ISGs)." (PMID 34298736, 2021). "Mutations in the IFNγ receptor IFNGR1, signaling adaptors JAK1 and JAK2 or components of the IFNγ signaling cascade, such as STAT1 and IRF1 were associated with cancer progression and immunotherapy resistance." (PMID 34201655, 2021). "IFNγ/STAT1-induced expression of caspases 1 and 8 has been reported in cancer cell lines, where STAT1 regulates Bcl-2 family members, including Bcl-xl, Bax, and Bak78–80." (PMID 34282238, 2021). "First, we leveraged a U3A cancer cell line, depleted for endogenous STAT1 and complemented with STAT1 WT or GOF mutants using lentiviral vector expression." (PMID 33679782, 2021). "STAT1 helps to maintain effective T-cell-mediated antitumor immune responses in different types of cancers." (PMID 34299314, 2021). "Previous study indicated that proteasomal degradation led to low expression of STAT1 in cancer 31, consistent with the data that proteasome inhibitors can prolong the activation and increase total expression of STAT1." (PMID 33391546, 2021). "This study discovered that hesperidin prevents IFN-γ-induced PD-L1 protein expression by inactivating STAT1/STAT3 signaling in OSCC cancer cells, contributing to tumors’ immune evasion." (PMID 34500779, 2021). "In this study, we investigated how cancer-cell-intrinsic IFN/STAT1 signaling regulates cell proliferation, mesenchymal phenotypes, and apoptosis in GSCs." (PMID 34771447, 2021). "The CAR‐T treatment markedly increased STAT1, cleaved‐caspase 3 and Bax expressions as the effector‐to‐target ratio increased in cancer cells, and the expression of caspase 3 was decreased to undetectable levels after exposure with CAR‐T cells." (PMID 33225580, 2021). "Current research has indicated that the expression of STAT1 is downregulated in a variety of tumor cells, and low STAT1 expression often indicates a poor prognosis for several types of cancers including HCC." (PMID 34458148, 2021). "Expression of the Stat1 downstream gene Mcl-1 increased in Oct4-overexpressing cancer cells, while Stat1 knockdown in Oct4-overexpressing cancer cells sensitized them to cisplatin-induced apoptosis." (PMID 34685622, 2021). "Ubiquitination and proteasomal degradation lead to STAT1 downregulation in several cancer types 20, and western blotting revealed dramatic dose-dependent increase in the STAT1 protein levels after MG132 treatment." (PMID 33391546, 2021). "To examine the function of the aberrant expression of STAT1 in the alisertib-treated cancer cells, we knocked down STAT1 and monitored the ability of alisertib to induce growth arrest and apoptosis in these alisertib-treated cells." (PMID 34522170, 2021). "For example, YTHDF1 expression had a strong association with STAT1 in Th1 cells, STAT6 in Th2 cells, STAT3 in Th17 cells, STAT5B in Treg cells, BCL6 in Tfh cells, and IRF5 in M1 macrophages in most cancer types." (PMID 34026603, 2021). "Exosomal αvβ6 integrin inhibited the signal transducer and activator of transcription 1 (STAT1)/MX1/2 signaling in cancer cells and reprogramed monocytes into the M2 phenotype." (PMID 33477340, 2021). "A series of in vitro experiment suggests that ELF-1- and/ or STAT1-dependent Lin28b regulation is responsible for Let-7 induction in Fhit-expressing cancer cells." (PMID 33437205, 2021). "High Stat1 expression exhibits resistance to genotoxic stress following treatment with doxorubicin and cisplatin or a combination of ionizing radiation in cancer cells." (PMID 34685622, 2021). "Signal transducer and activator of transcription 1 has been reported to be a key regulatory factor of angiogenesis that is one of the hallmarks of cancer." (PMID 33834023, 2021).
cancer (continued). "Data analysis of scRNAseq pan-cancer dataset confirmed the existence of a CXCL10+IRF1+ STAT1+ M1-type Mφ across human cancers displaying activation of antigen presenting and cross presentation gene programs." (PMID 34220848, 2021). "Consistent with our in vitro findings, trametinib has been reported to activate STAT1 and subsequent HLA-I induction in many other types of cancers." (PMID 34458148, 2021). "More importantly, the hsa05200 pathway derived from both ME and CNV signatures, which includes EGFR, KRAS, MDM2, STAT1 and other signature genes identified by us, is shown to be closely related to initiation and progression of cancer." (PMID 32030321, 2020). "(b) Prior studies have been under-powered in size and composition to detect cancer subtype-specific prognostic relevance of STAT1, as is observed in our CRC cohort (MSS vs. MSI subtype)." (PMID 32275681, 2020). "STAT1 is an important component in the NF-KB signal pathway, mediating cancer progression, and tumorigenesis." (PMID 32891166, 2020). "Bioinformatics studies demonstrated that miR-584 has a substantial role in cancer pathways and has the potential to target STAT1 transcripts." (PMID 32615958, 2020). "We identified STAT1 and IFN signaling as key regulatory targets of SPHK1 and demonstrated that an important mechanism by which SPHK1 promotes cancer cell survival is through the suppression of STAT1." (PMID 32260399, 2020). "The prognostic potential of STAT1 for cancers as reported up to date has been variable and sometimes even controversial." (PMID 32275681, 2020). "We also observed Tyr701 phospho-Stat1 is upregulated in a significant proportion of ESCC cancer samples." (PMID 33046973, 2020). "Together the data prove that Stat1 is needed to activate p16Ink4a in vitro and in vivo and that Stat1-mediated activation of Cdkn2a is needed to induce senescence in cancer cells." (PMID 32165639, 2020). "In consequence, cancer immune control required Stat1-mediated activation of the cell cycle regulators like p16Ink4a to stably arrest the growth of those cancer cells that are not eliminated by cytotoxicity." (PMID 32165639, 2020). "Western blot analyses showed that STAT1 forced transcription and synthesis of caspase 3 and caspase 7, which further initiated apoptotic processes in cancer cells." (PMID 33005420, 2020). "In consequence, the RT2.Stat1−/−-cancers differed from RT2.Stat1+/+-cancers selectively by their resistance to CIS." (PMID 32165639, 2020). "Since CSCs are the driving power of cancer development, recurrent, and chemoresistance and STAT1 influences the stemness of CSCs, a novel therapeutic strategy can be made by targeting STAT1 for the treatment of patients with PTX-resistance." (PMID 32516753, 2020). "Although STAT proteins play an essential role in cancer, research in the fields of immunology and oncology has mainly focused on STAT1/3." (PMID 32973222, 2020). "Combination therapy compared with anti-PD-1 monotherapy showed higher expression levels of PD-L1 on cancer cells due to increased secretion of IFNγ, which increased recruitment of STAT1." (PMID 33584714, 2020). "Even a recent meta-analysis of TAT1 in multiple types of tumors reported that the prognostic factor of STAT1 still depends on cancer type." (PMID 32793281, 2020). "Inhibition of caspases using the oligo caspase inhibitor zVAD-fmk (zVAD) in multiple of cancer cell lines enhanced or even derepressed the activation of STAT1 in CD95 stimulated cells." (PMID 31992798, 2020). "GH signaling plays a key role in cancer development and its activation can lead to STAT1, STAT3 and STAT5 signaling." (PMID 32582547, 2020).
cancer (continued). "As Stat1-positive and Stat1-negative RT2-cancers were similarly susceptible to lysis by cytotoxic CD8+ T cells, we depleted CD8 T cells with mAb before transplanting the cancer cells." (PMID 32165639, 2020). "Although SOCS1 levels were comparative between the normal and cancerous tissues, it was NPC tumors instead of para-carcinoma tissues that exhibited a strong immunostaining signal of STAT1, indicating the interrupted Inhibition of SOCS1 on STAT1 in NPC tumors." (PMID 32831137, 2020). "Under these circumstances cancer cells lose their sensitivity to IFNy by disrupting the IFNy-STAT1 signaling pathway and consequently antigen presentation via MHC-I molecules." (PMID 31196219, 2019). "Secondly, we detected an augmented baseline IFN-γ signature in BRCA1-mutated cancer and primary epithelial cells and tumors coupled with decreased cytotoxicity induced by IFN-γ or by STAT1 knockdown." (PMID 31840082, 2019). "Immunity-associated genes, like STAT1, whose downregulation by HPV has been reported, were found to be upregulated in almost all analyzed cancer tissues." (PMID 30918060, 2019). "The role of the JAK/STAT1 pathway in cancer remains under debate, with evidence showing both anti- and pro-tumorigenic functions across different cancers." (PMID 31382461, 2019). "In particular, COX2 upregulation has been demonstrated to promote immune suppression, metastasis, and drug resistance in several cancer types, with all features being consistent with chronic STAT1 activation." (PMID 31842362, 2019). "One of the prominent factors in inducing PD-L1 expression is the interferon-γ (IFN-γ) acting mainly via the JAK/STAT1/interferon regulatory factor (IRF) 1 pathway in multiple types of cancers." (PMID 31759368, 2019). "Although STAT1 has been found to be deregulated in a variety of cancers, the exact role of STAT1 in cancer, especially in different types of cells, remains controversial." (PMID 30456450, 2019). "Tissue microarray showed that the positive staining of total STAT1 and phospho-STAT1 on Y701 and S727 residues in serous ovarian borderline and malignant tumors only." (PMID 29751820, 2018). "The data indicate that STAT1 is an important component in the regulation of ERα transcription in ERα ‐positive cancer cells." (PMID 30334368, 2018). "We recently employed IHC staining of tissue microarrays and identified nuclear STAT1 expression in cancer cells as a beneficial prognostic factor for CRC patients." (PMID 29419930, 2018). "Other reported immune escape mechanisms that can play a role because of constitutive or adaptive EGFR-signaling are the expression of PD-L1 and the inhibition of antigen processing via dephosphorylation of STAT1 in cancer cells." (PMID 30192802, 2018). "We previously reported the anti-cancer progression role in signal transducer and activator of transcription 1 (STAT1) and nuclear factor of activated T-cells (NFAT)." (PMID 30400941, 2018). "In the present study, we found overexpression of STAT1 at both mRNA and protein levels in human epithelial-type ovarian borderline and malignant tumor tissues." (PMID 29751820, 2018). "Statistical analysis showed that the positivity of pSTAT1-Y701, pSTAT1-S727, and total STAT1 expression was significantly higher in ovarian borderline and malignant tumors compared with normal ovarian tissue (all P < 0.05)." (PMID 29751820, 2018). "Previous studies validated that STAT1 inhibition induces cancer cell proliferation, similar to that of miR-155 during the process of cell growth." (PMID 28418858, 2017). "Relevant habitats also had some pathways and cellular processes in common, including phosphorylation of STAT-1 and natural killer cell activity, consistent with cancer hallmarks." (PMID 29348883, 2017). "A number of studies have reported the relationship between STAT1 expression and the prognosis in various types of cancers; however, the results are controversial." (PMID 28536310, 2017).
cancer (continued). "We reasoned that inhibition of STAT1 would protect the OHCs while facilitating cisplatin-induced killing of cancer cells." (PMID 28703809, 2017). "This method can detect nitrated STAT1 down to picoMolar concentrations in PBMC samples derived from cancer patients." (PMID 29133913, 2017). "An analogous process occurs for STAT1 in that phosphorylation of STAT1 is a natural product of interferon signaling and the protein is nitrated in immune cells when exposed to cancer derived myeloid derived suppressor cells." (PMID 29133913, 2017). "Mechanistically, MBZ can modulate the cancer-associated pathways including ELK1/SRF, AP1, STAT1/2, MYC/MAX, although the regulatory outcomes are context-dependent." (PMID 28099902, 2017). "By using a panel of previously well-characterized cancer-associated pathway reporter analyses, we found at least four pathways, e.g., ELK1/SRF, AP1, STAT1/2, MYC/MAX, are significantly affected." (PMID 28099902, 2017). "Previous work showed that IFN-γ significantly upregulated HLA-ABC expression in several cancer cell lines and increased STAT1 expression." (PMID 28881828, 2017). "STAT1 has also been shown to act as a driver in cancers, modulating downstream MYC expression, which in turn promotes the capacity for proliferation, migration, and invasion of cells." (PMID 28129744, 2017). "In conclusion, proteomic data indicate that IL-27 shows broadly overlapping functions with IFN-γ, in human cancer cells, most likely in relationship to the common usage of the STAT1 pathway." (PMID 27683036, 2016). "Of note, there are six members in the STAT family of which STAT1, STAT3 and STAT5 are highly associated with cancer, but SC09 specifically inhibits STAT3 activation thus inducing cancer cell death." (PMID 27705908, 2016). "STAT3, another member of our network has also been heavily involved in cancers where STAT1 is upregulated." (PMID 27295045, 2016). "We therefore suggest taking STAT2 protein expression into account when assessing STAT1 bioactivity, including as predictor of prognosis in cancer and disease development." (PMID 27780205, 2016). "Perhaps more importantly, it induced the expression of the immune-suppressive molecules IDO and PD-L1, in human cancer cells, through the activation of STAT1 or STAT3 pathways, respectively." (PMID 27683036, 2016). "Although a few reports indicated STAT1 promoted cancer progression, it has been widely accepted that STAT1 negatively regulates cancer progression." (PMID 26928402, 2016). "HDAC4 has been proposed to contribute to cisplatin resistance of cancer cells by promoting STAT1 deacetylation." (PMID 25504437, 2015). "Phosphorylation of signal transducer and activator of transcription 1 and Bad reduces bortezomib-mediated apoptosis in cancer cells." (PMID 26398947, 2015). "IFNγ/STAT1 signaling has therefore been suggested to exhibit both pro- and antitumor properties, depending on the context and cancer type." (PMID 26654227, 2015). "Altogether these data show, for the first time, that IL-27 induces IDO and PD-L1 expression in human EOC cancer cells through activation/phosphorylation of STAT1 or STAT3, respectively." (PMID 26657115, 2015). "STAT1 overexpression protects cancers from DNA-damaging agents including radiation therapies and chemotherapies in different cancer types." (PMID 24460726, 2014). "The miR-29 family directly targets IFN-γ, and IFN-γ-induced Stat1 can up-regulate miR-29 expression; in cancer cells, miR-145 directly targets Stat1 and c-Myc, and miR-378 targets the IFN-γ receptor 1, IFNGR1, to suppress bovine luteal cell apoptosis." (PMID 24800866, 2014). "We concluded that the STAT1 is the dominating pathway in cancer cell lines following their interaction with activated T lymphocytes." (PMID 24911872, 2014).
cancer (continued). "The initial proteomic analysis indicated that among some of the major signaling pathways known to be key in cancer cells, activated STAT1 and STAT3, were differentially expressed and therefore potentially interesting signaling candidates in resistant cells." (PMID 24728078, 2014). "Treatment of 18Co fibroblasts with the proinflammatory cytokine TNFα interfered with their ability to trigger STAT1 signaling in cancer cells." (PMID 24818101, 2014). "Several studies have demonstrated that chemotherapeutic agents, such as doxorubicin, docetaxel or anthracyclines enhance the expression of STAT1 and its activation in chemo-resistant cancer cells." (PMID 24886089, 2014). "Collectively, these results suggest that elevated IFN-γ expression by activated PBMCs and STAT1 activation in cancer cells play an important role in HER2 downregulation in cancer cells by the co-treatment of PBMCs and trastuzumab." (PMID 24693969, 2014). "We first confirmed that IDO expression in our cancer cell line model was dependent on STAT1 signaling following exposure to IFN-γ or CD3-activated T lymphocyte supernatant." (PMID 24911872, 2014). "In 10 cancer cell lines, STAT1 expression correlated with resistance to doxorubicin and topoisomerase-II inhibitors." (PMID 24460726, 2014). "This study demonstrates that active engagement of immune effector cells and high HER2-expressing cancer cells by trastuzumab induces HER2 downregulation through the increased secretion of IFN-γ by immune cells and activation of STAT1 in cancer cells." (PMID 24693969, 2014). "We showed in this study that total STAT1 protein and phosphorylation of STAT1 were increased in cancer cells with HER2 downregulation." (PMID 24693969, 2014). "In this study, we aimed to inhibit IDO expression induced by IFN-γ by targeting STAT1 signaling in cancer cell lines." (PMID 24911872, 2014). "In various cancer cell types, STAT1 has been previously reported to be an important mediator for NF-κB, which is known to play a critical role in carcinogenesis and chemoresistance in ESCC." (PMID 25355139, 2014). "Activation of 18Co cells with TNF, a cytokine that plays a major role in the pathology of CD, was sufficient to prevent STAT1 activation in carcinoma cells." (PMID 24818101, 2014). "Most importantly, Cox multivariate analysis demonstrated that the density of CD33+/p-STAT1+ cells within the cancer tissue was an independent prognostic factor." (PMID 23307253, 2013). "A number of studies have reported up-regulation of the Ifn-γ/Jak/Stat1 pathway in cancer cell lines and xenograft models that developed resistance to chemotherapeutic agents and/or irradiation." (PMID 23520493, 2013). "The “interferon response genes regulated by STAT1” showed a strikingly coherent variation in expression among these patients with cancer, which enabled them to be divided into two groups." (PMID 22235336, 2012). "Correlated parameters and parameters with one finite confidence interval helped to explain differences between IFNγ-induced STAT1 signalling in stellate and cancer cells." (PMID 23284277, 2012). "We used mathematical modeling, simulations and parameter identifiability analysis to explain experimentally observed differences of IFNγ-induced STAT1 signalling in pancreatic stellate cells and cancer cells." (PMID 23284277, 2012). "Chrysin shows in vitro anti-cancer activity that is correlated with induction of histone hyperacetylation and possible recruitment of STAT-1, 3, 5 proteins at STAT (−692 to −684) region of p21 promoter." (PMID 22591439, 2012). "Together, these results indicate that the cancer cells are less sensitive towards IFNγ than pancreatic stellate cells, and suggest a less efficient activation of STAT1 signaling as a possible molecular explanation." (PMID 21310022, 2011).